VIM (vimentin)
Diseases named in the same sentence as VIM in open-access papers (continued):
Sharing a sentence is not in itself a finding about the gene and the disease.
viral infection (continued). "We observed a significant increase in the expression of Sn, CD163, and vimentin following viral infection." (PMID 39568484, 2024). "Previous studies have demonstrated a rapid increase in vimentin expression in response to inflammatory stimuli consequent to viral infection." (PMID 39866583, 2024). "Vimentin plays a key role in the viral adsorption and entry process, which is the initial and crucial step of viral infection." (PMID 37848995, 2023). "Viral infection can trigger the rearrangement of vimentin filaments, an event closely related to virus replication." (PMID 37848995, 2023). "What is the precise underlying mechanism governing the contrasting interactions between vimentin and HN proteins during viral infection?" (PMID 37848995, 2023). "Vimentin can play a dual role in viral infection by serving as a coreceptor for SARS-CoV and SARS-CoV-2 to enhance viral attachment, while it can also impede the attachment of AIV by disrupting the formation of lipid rafts on the surface of host cells." (PMID 37848995, 2023). "In summary of earlier studies, vimentin plays important roles in viral infection and lung injury in the following ways: a." (PMID 35646741, 2022). "Treatment with anti-vimentin antibodies considerably decreased the virus infection, which shows the direct role of surface vimentin in the binding of virus spike proteins." (PMID 35573702, 2022). "A more comprehensive elaboration on the role of vimentin during host-virus interactions in a wide range of viral infections is described elsewhere." (PMID 35573702, 2022). "The nonstructural protein 3A of the foot-and-mouth disease virus (FMDV) can directly interact with VIM and maintains the viral replication, but the overexpression of VIM suppressed the viral replication, whereas VIM knockout promoted virus infection." (PMID 36108090, 2022). "This study has important reference value for exploring the function and mechanism of vimentin and lipid metabolism on viral infection and provides an insight for antiviral targets development against AIV." (PMID 36016436, 2022). "For some viral infections, expression of Vimentin intermediate filaments on the cell surface aid at an early stage of infection as a co-receptor for the entry into the host cell." (PMID 35573702, 2022). "Vimentin is closely related to intracellular lipid metabolism, which plays an important role during the viral infection process." (PMID 36016436, 2022). "Following on from studies investigating the role of vimentin in virus infection, we employed acrylamide to collapse the vimentin filament network." (PMID 33792166, 2021). "A growing body of evidence indicates the importance of vimentin overexpression in viral diseases with a rapid onset and long course." (PMID 34372621, 2021). "Meanwhile, the protein expression of vimentin in the spleen tissues was significantly increased during viral infection (a fold-change of 1.4 (p = 0.004) for Erfurt, and a fold-change of 1.4 (p = 0.01) for Rossi)." (PMID 34372621, 2021). "Downregulation of VIM mRNA during viral infection of RHDVa was detected in the lung tissues (40% reduction for both strains: p = 0.04 for Erfurt and p = 0.02 for Rossi vs. the control)." (PMID 34372621, 2021). "In the context of viral infections, recombinant vimentin has been shown to limit cell internalization of human papilloma virus 16 pseudovirions and to reduce enterovirus 71 virus infection in cellular models." (PMID 32630064, 2020). "Conversely, vimentin expression has been observed to be negatively affected by virus infection in some cases." (PMID 32630064, 2020). "Numerous studies on pathogen invasion have been carried out in vitro using cancer epithelial or fibroblast-like cell lines, which express vimentin, like the Vero cell line that is frequently used in the study of viral infections." (PMID 32630064, 2020).
viral infection (continued). "Heparan sulfate proteoglycans, P-selectin glycoprotein ligand-1, sialylated glycan, annexin II, vimentin, fibronectin, and prohibitin enhance viral infection by retaining the virus on the cell surface." (PMID 31924205, 2020). "One more example in African swine fever virus provided more details in the mechanism of vimentin during viral pathogenesis, suggesting that phosphorylation and rearrangement of vimentin occurred after virus infection." (PMID 26801988, 2016). "The viral infection was only blocked by 13.2% and 8.9% of plaque reductions with vimentin head and tail proteins, respectively." (PMID 27910934, 2016). "Several previous studies have suggested that vimentin plays an important role in several virus infections." (PMID 27603133, 2016). "Major changes in the distribution of vimentin are observed when the cell moves and divides, but this protein is also redistributed in cells expressing misfolded proteins and during virus infection." (PMID 23855489, 2013). "In the present study, we investigated the involvement of vimentin in EV71 replication and the effects of virus infection on vimentin structure." (PMID 24073199, 2013). "It has been shown that viral infection changes the dynamic morphology and structure of cytoskeletal components such as microtubules, keratins 18 and 8, vimentin (intermediate filaments) and also the actin filaments." (PMID 23082182, 2012). "However, recent studies have revealed that IFs, particularly vimentin and keratin, exert a profound and versatile influence on viral infection." (PMID 41867121, 2026). "Additionally, we used ajoene to examine vimentin rearrangement’s direct effects on TJs and viral infection in HD11 cells." (PMID 40880512, 2025). "Immunofluorescence staining revealed that the enhanced green fluorescent protein (EGFP), transmitted by the AAV1/2 virus, extensively colocalized with areas positively stained by the tdTomato and vimentin antibodies, indicating effective viral infection of tanycytes." (PMID 39975575, 2025). "In the context of virus infection, vimentin plays an important role in virus entry and replication." (PMID 39616228, 2024). "Vimentin in saliva has been investigated as a biomarker for oral cancers, but not to our knowledge in relation to viral infection susceptibility." (PMID 38007005, 2024). "Using ALI-COs, a highly accessible slice culture version of whole-cortical organoids for viral infections, with improved oxygenation, nutrition and longevity, we also observed that vimentin also collapsed in infected cells, similar to what was previously observed in Vero and U251 cells." (PMID 39394194, 2024). "Interestingly, evidence is mounting that vimentin plays an essential role in coordinating the signaling pathways that regulate inflammatory response mediator levels in viral infection and is a ligand for specific pattern recognition receptors (PRRs)." (PMID 38535592, 2024). "Viral infection can also trigger vimentin rearrangement, which contributes to viral replication." (PMID 37848995, 2023). "Finally, during viral infection, vimentin can also form vimentin cages that facilitate viral replication and protein production of viruses." (PMID 37475865, 2023). "Moreover, the varied impacts of vimentin on viral infection eventually lead to differences in NDV replication efficiency." (PMID 37848995, 2023). "Upon viral infection, vimentin is crucial for stress response and signal transduction in cells." (PMID 37376653, 2023). "Vimentin has been demonstrated to play a key role in numerous stages of viral infection." (PMID 37848995, 2023). "Additionally, it has also been described an interesting participation of vimentin against certain viral infections." (PMID 36769377, 2023). "In addition, vimentin expression was significantly increased in MβCD-treated HeLa cells with the viral infection and returned to normal levels after exogenous cholesterol to backfill the MβCD-treated cells." (PMID 36016436, 2022).
viral infection (continued). "Additionally, it was observed that compared to that of HeLa cell control, NP protein expression was increased in KO-vimentin cells with viral infection." (PMID 36016436, 2022). "Meanwhile, vimentin-coated viruses may bind and aggregate with anti-vimentin antibodies, thereby inhibiting viral infection and promoting viral clearance." (PMID 35646741, 2022). "During viral infections, surface VIM can act as a binding protein; however, intracellular VIM is involved in the internalization of clathrin-coated endosomes, attachment, and transport of capsids along microtubules, and acidification of and capsid release from endosomes." (PMID 34571970, 2021). "Moreover, the presence of vimentin in specific virus-targeted cells and its induction by proinflammatory cytokines and tissue damage contribute to its implication in viral infection." (PMID 32630064, 2020). "Additional studies have shown relevant roles for vimentin during viral infections." (PMID 32630064, 2020). "In addition to recognition of PTM-altered vimentin, molecular mimicry-dependent cross-reactivity has been related to the development of autoimmune disease as a consequence of bacterial or viral infections." (PMID 32630064, 2020). "Meanwhile, only three proteins that displayed regulated expression in both H5N1-infected CEF cells at all the time points were ACTG1, LMNB2 and vimentin, which are cytoskeleton protein that is generally expressed in normal cells and reorganized after virus infection." (PMID 28079188, 2017). "Nevertheless, several studies confirmed that vimentin is indispensable for viral infection." (PMID 27910934, 2016). "The inhibition could occur when DENVs were pre-incubated with the vimentin rod proteins or when HUVECs were pre-treated with V4630 PcAb against vimentin rod prior to viral infection." (PMID 27910934, 2016). "The phosphorylation of vimentin could also play a role in viral infection, where the viral nucleic acids may be recognized by Ku and DNA-PK in the cytoplasm." (PMID 24282534, 2013). "Thus the distribution of VP2 and vimentin was assessed at early (8 hours) and late (24 hours) timepoints following virus infection." (PMID 17224050, 2007). "Since vimentin is involved in bacterial and viral infections, and consequently induces inflammatory responses, which in severe cases can be life-threatening, developing drugs targeting vimentin could have the effect of controlling bacterial and viral infections." (PMID 40061451, 2025). "Furthermore, this study broadens our understanding of the diverse functions of vimentin during viral infection and indicates that vimentin may play a broader spectrum effect in viral cell–cell transmissions beyond HCV, as a unique host factor." (PMID 39611409, 2025). "In vitro studies have repeatedly showed that extracellular vimentin (eVIM) promotes the penetration of viruses by acting as an adhesion factor, suggesting that reducing eVIM density in the blood could be an effective approach to treat viral infections." (PMID 41055051, 2025). "Vimentin expression may depend on IFNs, and viral infection may promote vimentin promoter activity." (PMID 37376653, 2023). "Increasing evidence indicates that vimentin could play a key role in viral infections." (PMID 34372621, 2021). "Additionally, Vimentin plays important roles during viral infection and replication cycles." (PMID 33379366, 2020). "In addition, vimentin is required for assembly and activation of the NLRP3 inflammasome, which mediates the induction of pro-inflammatory cytokines associated with acute lung injury in bacterial and viral infections." (PMID 32630064, 2020). "However, in virus-infected cells, vimentin accumulated around the area of virus-infection and could co-localize with NP in the cytoplasm, indicating that virus infection induced vimentin reorganization." (PMID 28079188, 2017).
viral infection (continued). "Therefore, superficial vimentin may be a versatile host factor for viral infection, but the exact binding sites in vimentin may vary in different species of viruses." (PMID 27910934, 2016). "In addition, virus infection of vimentin-positive cells could be related to the occurrence of a new, histogenetically different cell type or may be related to defects in virus replication, transcription and translation due to intrinsic and extrinsic factors." (PMID 24992230, 2014). "Several results suggest that vimentin could play a role in viral infection." (PMID 24282534, 2013). "On the other hand, it has been reported that vimentin prevents the internalization of HPV16, and its expression is inversely correlated with the viral infection." (PMID 36769377, 2023). "Additionally, upon viral infection, vimentin expression is increased, which may be influenced by IFN receptor 1 (IFNAR1), a nonspecific factor triggered by almost all viral infections, can inhibit TBK1 and IKKε during the process of enhanced vimentin expression." (PMID 37376653, 2023). "It seems that the putative PRRSV receptors, CD151, integrin and vimentin, primarily expressed on PGE mediates viral infection and cellular responses at the early infection." (PMID 37099541, 2023). "Vimentin, an important type III intermediate filament cytoskeletal protein, has been widely reported to be involved in multiple steps of viral infection." (PMID 37848995, 2023). "It was reported that cytoplasmic vimentin is translocated to the cell surface, where it interacts directly with the SARS-CoV spike protein during viral infection, serving as a putative coreceptor involved in cell entry of SARS-CoV." (PMID 35683351, 2022). "Our results seem to confirm that hzVSF-v13 may offer a synergistic advantage as compared with other treatments that do not target vimentin, as vimentin has a twofold role in the disease, both in viral infection and in the associated life-threatening lung inflammation." (PMID 35683351, 2022). "However, the function of secreted vimentin in virus infection remains unknown." (PMID 27910934, 2016). "Vimentin is a type III intermediate filament protein that maintains cellular integrity, organelle positioning, and resilience to mechanical stress, but it is increasingly recognized for its dynamic change in viral infection." (PMID 41516263, 2025). "Furthermore, and of utmost importance for our research, vimentin has been reported to prevent the internalization of HPV16, while its expression has been inversely correlated with viral infection." (PMID 36769377, 2023). "Specifically, the B domain (109-174AA) of Annexin A2 binds to vimentin, a cytoskeletal component, and the Annexin A2-vimentin complex then binds to the N structural protein of PRRSV, which may promote virus infection." (PMID 37482693, 2023). "In contrast, WSN induced more N-cadherin, β-catenin, vimentin, snail, cyclin D, PPAR, TCF-1, and TGF-β expression than Yamagata at 12 and/or 24 h after virus infection." (PMID 35283846, 2022). "Although VIM present on SH-SY5Y cells interacted with DENV-3 in VOPBA; infection inhibition assay using anti-VIM antibodies did not inhibit the virus infection indicating that it is merely an interacting protein." (PMID 32306962, 2020). "Despite the abundance of such reports, there is still no consensus on the role played by vimentin during virus infections." (PMID 31619557, 2020). "The expression level of the superficial vimentin on VECs was not affected by viral infection or siRNA interference, indicating that the protein exists in a particular mode." (PMID 27910934, 2016). "If the binding of vimentin rod domain to DENV-2 EDIII mediates the DENV infection of VECs, then the viral infection could be inhibited." (PMID 27910934, 2016). "Vimentin is a major component of type III intermediate filaments that has been reported to be redistributed in cells around sites of virus replication and assembly during virus infection." (PMID 22463732, 2012).
viral infection (continued). "In our study, both the phosphorylation and solubility of vimentin were highest at 12 h after viral infection, whereas the level of protein expression did not follow this trend, which indicates that vimentin expression, phosphorylation, and solubility are all regulated by DENV-2 infection." (PMID 35433510, 2022). "In addition, other PRRs might interact with vimentin as well, such as RIG-I-like receptors that can sense viral infections." (PMID 27096872, 2016). "Vimentin is a type III intermediate filament (IF) protein expressed in mesenchymal cells, that is often used as a marker of mesenchymal derived cells or cells undergoing an epithelial-to-mesenchymal transition (EMT), and was reported participated in virus infection." (PMID 26544179, 2015). "However, increasing the concentration of vimentin antibodies or exogenous vimentin was not sufficient to completely block viral infection, suggesting that vimentin acts as an early cofactor in virus entry rather than being essential for the infection process itself." (PMID 40006936, 2025). "For the alphavirus of the Togavirus family, studies showed that virus infection induced the destruction of the action network, but did not destroy the intermediate filaments of the vimentin, which declared that the vimentin may play an important role in the replication of alphaviruses." (PMID 37928675, 2023). "Thus, the upregulation of VIM at the cell surface is contingent on the health status of the liver and may not be entirely depend on viral infection." (PMID 34571970, 2021). "Vimentin-positive cells of glial or nonglial origin should, thus, be considered as a contributing factor in advanced distemper lesions and might represent a new target for virus infection." (PMID 24992230, 2014).